NPY (neuropeptide Y)
Diseases named in the same sentence as NPY in open-access papers (continued):
Sharing a sentence is not in itself a finding about the gene and the disease.
Hepatic fibrosis (5 papers, 2019 to 2025). The presence of excessive fibrous connective tissue in the liver. "Nevertheless, limited information exists regarding the relationship between NPY and HSCs activation, the fibrogeneic response, and even hepatic fibrosis." (PMID 31263154, 2019). "What’s more, it has been shown that neuropeptide (NPY) is upregulated in human MASLD and that B cells may require dipeptidyl peptidase 4 (DPP4) to contribute to CCL4-induced hepatic fibrosis via NPY to induce maximal collagen production (Wang XM." (PMID 40761743, 2025). "Overall, the role of NPY during liver fibrosis and its mechanisms need to be further investigated." (PMID 36497043, 2022). "In the progression to hepatic fibrosis, NPY might also be a key player, as neprilysin-mediated cleavage of NPY resulted in fragments, that were held responsible for the activation of genes, which direct hepatic stem cells to develop towards fibroblast-like cells." (PMID 38542814, 2024). "However, there is no report about whether ghrelin can influence liver fibrosis progression through regulating NPY expression, although ghrelin has been reported to exert an anti-fibrotic and anti-inflammatory effect on the liver." (PMID 36497043, 2022).
hyperprolactinemia (5 papers, 2017 to 2024). Abnormally high level of prolactin in the blood. "As well, hyperprolactinaemia can induce the expression of neuropeptide Y (NPY), agouti‐related peptide (AGRP) and corticotrophin releasing hormone (CRH) which increase appetite and body weight." (PMID 39663784, 2024). "On the other hand, suckling, which induces hyperprolactinemia, can stimulate the activation of hypothalamic NPY neurons, suggesting that NPY is modulated by prolactin (PRL) during lactation." (PMID 29383163, 2017).
inflammatory bowel disease (5 papers, 2012 to 2025). A spectrum of small and large bowel inflammatory diseases of unknown etiology. "Elevated levels of NPY have been reported in the serum of patients with inflammatory bowel disease (IBD)." (PMID 41007974, 2025). "Significantly decreased levels of NPY have also been observed in patients suffering from inflammatory bowel disease (IBD)." (PMID 23305360, 2012). "Intestinal NPY, PYY, and PP are reported to be abnormal in patients with inflammatory bowel disease and its animal models with increased plasma IL-6." (PMID 29429048, 2018).
liver steatosis (5 papers, 2010 to 2024). "Next, the mechanisms underlying the attenuation of hepatic steatosis by NPY deficiency were investigated." (PMID 34829968, 2021). "Together, these results suggest that NPY deficiency improved HFD-induced hepatic steatosis, possibly through the downregulation of fatty acid transport and Tg synthesis." (PMID 34829968, 2021). "Furthermore, NPY deficiency ameliorated HFD-induced fatty liver by regulating genes involved in fatty acid uptake and Tg synthesis, including Cd36, Lpl, Dgat2, and Cyp4a14." (PMID 34829968, 2021). "To examine whether NPY deficiency ameliorates hepatic steatosis, we performed H&E staining, oil red O staining, and measured the triglyceride (Tg) content in the liver." (PMID 34829968, 2021). "Data on effects of modulators of the NPY system on liver steatosis are rare, but it was demonstrated that NPY knockout results in alleviated liver steatosis in HFD-induced obese mice." (PMID 38542814, 2024). "NPY is known to be involved in adipose tissue inflammation and liver steatosis." (PMID 37755786, 2023). "In contrast to NPY antagonists, GLP-1 receptor agonists (e.g., semaglutide) are studied widely and showed positive effects on liver steatosis." (PMID 38542814, 2024). "NPY deletion alleviated HFD-induced adipose inflammation and liver steatosis." (PMID 34829968, 2021).
melanoma (5 papers, 2015 to 2023). A malignant, usually aggressive tumor composed of atypical, neoplastic melanocytes. "High NPY expression has been associated with invasiveness in melanoma, and a low NPY expression with increased cell proliferation and high peritumoral mast cell infiltrates in primary cutaneous melanoma." (PMID 37373115, 2023). "Recent murine and human studies approached the possible association between neuropeptide Y and melanoma." (PMID 34068618, 2021). "In a sample size of 49 primary tumors, Gilaberte and colleagues also reported high NPY expression in primary melanomas which were associated with higher probability of metastasis, such as vertical growth phase with low or no tumor lymphocytic infiltration response." (PMID 35418942, 2022). "In a follow-up study, Perez Tato and colleagues evaluated 79 primary tumors and found that superficial spreading melanoma and lentigo maligna exhibit significantly higher levels of NPY expression in comparison to nodular melanoma." (PMID 35418942, 2022). "Initial reports of NPY expression in primary cutaneous melanomas found that NPY is lowly expressed in melanocytic nevi and highly expressed within the cytoplasm by many types of melanoma tumors." (PMID 35418942, 2022). "NPY expression has been reported in cutaneous melanoma; this expression was higher in melanomas than in melanocytic nevi, and nodular melanomas showed the highest median percentage of tumor cells expressing NPY, followed by superficial spreading melanomas." (PMID 37373115, 2023). "Interestingly, in mice injected subcutaneously with B16-F10 mouse-derived melanoma cells, sympathectomy to reduce sympathetic neurotransmitters (like NPY and noradrenaline) prior to tumor initiation greatly attenuates melanoma growth and yields smaller tumors." (PMID 35418942, 2022). "Therefore, NPY and its Y2 receptor are promising new targets in melanoma tumor therapy." (PMID 26153206, 2015). "Thus, it seems that NPY and its Y2 receptor antagonist might be new targets in melanoma tumor therapy." (PMID 26153206, 2015). "However, melanoma metastases and lentigo malign melanomas did not express NPY." (PMID 37373115, 2023).
pancreatic cancer (5 papers, 2022 to 2025). "For instance, NPY promotes breast cancer metastasis by stimulating endothelial cell migration via Y2 receptors, while SP enhances pancreatic cancer proliferation by activating neurokinin-1 receptor (NK1R)-mediated ERK signaling." (PMID 40805163, 2025). "NPY, Y1R, and Y2R expressions have been studied in human pancreatic ductal adenocarcinomas and a mouse model of pancreatic cancer." (PMID 37373115, 2023). "Given the role of NPY in promoting disease progression in various other cancers, we aimed to determine whether NPY signaling could also affect pancreatic tumor development and progression." (PMID 40073121, 2025). "Interestingly, various solid tumors, including breast, lung, and pancreatic cancers, ectopically express neuropeptides such as Neuropeptide Y (NPY), Substance P (SP), and Vasoactive Intestinal Peptide (VIP), mediating communication between neurons, immune cells, and cancer cells." (PMID 40805163, 2025).
peripheral nerve injury (5 papers, 2010 to 2019). Injury to a peripheral nerve. "These authors also suggest that NPY and galanin may work together in partnership in the modulation of neuropathic pain caused by severe peripheral nerve injury." (PMID 31620455, 2019). "Similarly to GAL, NPY is also involved in the modulation of neuropathic pain induced by peripheral nerve injury." (PMID 31023212, 2019). "Furthermore, it has been suggested that NPY can be released intraganglionically, especially after peripheral nerve injury, and act as a mediator of chemical cell-to-cell signalling." (PMID 22769424, 2012). "Thus, the expression of PAP-II can be induced in large DRG neurons that express NPY 14 days after peripheral nerve injury." (PMID 20420691, 2010). "It is known that neuropeptide Y (NPY) is expressed at very low levels in DRG neurons of normal rats, but its expression is markedly up-regulated in large DRG neurons after peripheral nerve injury." (PMID 20420691, 2010).
pheochromocytoma (5 papers, 2000 to 2023). "It has been suggested that the plasma NPY level could be used as an early diagnostic marker for pheochromocytomas and paragangliomas in patients who received treatments that interfere with catecholamine reuptake or suffer from severe kidney impairment." (PMID 37373115, 2023). "NPY is released from pheochromocytomas, and nitric oxide favors the release of NPY from rat pheochromocytoma PC12 cells." (PMID 37373115, 2023). "Plasma NPY increased during the surgical removal of human pheochromocytoma tumors, and this level remained high until tumor resection." (PMID 37373115, 2023). "Lower NPY levels were observed in pheochromocytomas from von Hippel-Lindau patients (noradrenergic phenotype) when compared with pheochromocytomas from multiple endocrine neoplasia type 2 patients (adrenergic phenotype)." (PMID 37373115, 2023). "Plasma NPY levels were higher in pheochromocytoma patients with left ventricular hypertrophy than those without left ventricular hypertrophy." (PMID 37373115, 2023). "NPY is a neurotransmitter whose high plasma levels are found in several cancers, including pheochromocytoma, ganglioma, and neuroblastoma, in which it can be used as a marker." (PMID 37685358, 2023). "Despite the measurement of catecholamines displaying a higher sensitivity in pheochromocytoma and paraganglioma, NPY may be a viable alternative in patients suffering from kidney impairment or under treatments that interfere with catecholamine reuptake." (PMID 37685358, 2023). "Moreover, NPY exerted a mitogenic action promoting left ventricular hypertrophy in patients with pheochromocytoma." (PMID 37373115, 2023). "In addition to secreting the catecholes dopamine, epinephrine and norepinephrine, numerous other hormones have been isolated from pheochromocytomas including adrenocorticotropin, vasoactive intestinal peptide, neuropeptide Y, IL-6, calcitonin, and chromogranin A." (PMID 21843357, 2011).
rheumatoid arthritis (5 papers, 2010 to 2022). A chronic, systemic autoimmune disorder characterized by inflammation in the synovial membranes and articular surfaces. "Plasma levels of NPY are reported to be elevated in other complex multi-symptom illnesses associated with immunologic dysfunction, including rheumatoid arthritis (RA) and systemic lupus erythematosus (SLE)." (PMID 21190576, 2010). "Changes in the density of sympathetic nerve fibers, which are characterized by tyrosine-hydroxylase (TH) or neuropeptide Y (NPY) or both, in synovial tissue contribute to rheumatoid arthritis (RA)." (PMID 25789373, 2014). "The role of NPY on autoimmune inflammatory diseases such as rheumatoid arthritis (RA) is not completely understood." (PMID 32377539, 2020). "A cross-sectional design of rheumatoid arthritis (RA) patients found that serum levels of NPY are significantly related to TNF-α levels and disease activity in RA independently of IL-6, TNF-α, or leptin levels." (PMID 35273572, 2022).
stress-related disorder (5 papers, 2018 to 2022). Stress-related disorders are mental health disorders that are a result of an atypical response to both short and long-term anxiety due to physical, mental, or emotional stress. "In humans, studies related NPY with resilience to stress and lower levels of it with stress-related disorders like PTSD." (PMID 32867327, 2020). "Clinical studies have linked variations in plasma NPY and polymorphisms in genes for NPY and its receptors with PTSD, making this system an attractive pharmacotherapeutic target for stress-related disorders." (PMID 29867615, 2018). "Furthermore, human studies suggest that NPY delivered intranasally can demonstrate therapeutic effects for stress-related disorders in females and in a dose-dependent fashion." (PMID 34566592, 2021). "Thus, intranasal NPY shows promise as a putative effective treatment for stress-related disorders in males." (PMID 32867327, 2020).
subarachnoid hemorrhage (5 papers, 2021 to 2025). A serious neurological disorder characterized by intracranial hemorrhage into the subarachnoid space. "The vaso- and psychoactive endogenous Neuropeptide Y (NPY) has repeatedly been shown to be excessively released after subarachnoid hemorrhage and in numerous psychiatric disorders." (PMID 38425753, 2023). "Additionally, in basic and clinical experimental research on subarachnoid hemorrhage (SAH) in animal models and in humans, NPY has repeatedly shown to be excessively released into the cerebrospinal fluid (CSF) and into serum." (PMID 38425753, 2023).
type 1 diabetes (5 papers, 2011 to 2023). "Insulin deficient type 1 diabetes exhibits hyperphagia and is associated with increased expression of NPY in ARC." (PMID 22081645, 2011). "Insulin deficient type 1 diabetes exhibits increased expression of NPY and hyperphagia." (PMID 22081645, 2011). "In subjects with type 1 diabetes, C-peptide-NPY elicits the highest interferon-γ response, C-peptide-IAPP2 the highest IL-10 and IL-17 responses were observed at a similar magnitude for C-peptide-IAPP1, C13-32, and C22-A5." (PMID 34262563, 2021). "However, administration with Sitagliptin relieved the mild changes in the hippocampal NPY system of early type 1 diabetic rats." (PMID 33973530, 2021).
Arthritis (4 papers, 2010 to 2026). Inflammation of a joint. "Evaluation of the mRNA expression for the orexigenic NPY in the ARC showed its upregulation during arthritis." (PMID 20953376, 2010). "In addition, food-restriction led to a more profound decrease of mRNA expressions for anorexigenic factors (POMC, CART, IL-1β) and marked increase of mRNA expressions for orexigenic factors (NPY, AgRP) compared to the other dietary regimes with or without arthritis." (PMID 20953376, 2010).
atrial fibrillation (4 papers, 2018 to 2025). A disorder characterized by an electrocardiographic finding of a supraventricular arrhythmia characterized by the replacement of consistent P waves by rapid oscillations or fibrillatory waves that vary in size, shape and timing and are accompanied by an irregular ventricular response. "In patients with paroxysmal atrial fibrillation, tragus stimulation reduces inflammatory cytokines and supresses atrial fibrillation and NPY levels." (PMID 38847435, 2025).
autism (4 papers, 2021 to 2026). Persistent deficits in social interaction and communication and interaction as well as a markedly restricted repertoire of activity and interest as well as repetitive patterns of behavior. "Additionally, other peptides can be administered intranasally like oxytocin, neuropeptide Y, and novel metabolic modulators for neuroprotection and affective disorders (AD, autism, Down syndrome)." (PMID 41898218, 2026). "The hypothalamic circuitry implicated by these data suggest impaired excitation of AgRP/NPY feedback inhibitory neurons may explain the increased aggression behavior found in genetic forms of autism." (PMID 36909588, 2023). "Therefore, the decreased number of NPY-positive cells in the adult mouse visual cortex was found to be related to animal model of autism." (PMID 33546356, 2021).
bulimia nervosa (4 papers, 2011 to 2023). A disorder characterized by recurrent episodes of binge-eating over which the individual feels a lack of control; these episodes of binge-eating are followed by recurrent compensatory behavior to prevent weight gain, usually self-induced vomiting. "Status of bulimia nervosa was found to be positively correlated with plasma levels of NPY, obestatin and PYY, and negatively with leptin levels." (PMID 22681985, 2012). "Endocrine perturbations and a dysfunction within the FFA-leptin-NPY-GH system may also take part in the etiopathogenesis of either bulimia or AN." (PMID 22093818, 2011). "It would also be valuable to compare NPY and PYY levels across the whole spectrum of ED, including patients with bulimia nervosa and binge eating disorders." (PMID 33670342, 2021).
gastric cancer (4 papers, 2022 to 2025). A primary or metastatic malignant neoplasm involving the stomach. "Plasma NPY concentration is decreased in patients with colorectal or gastric carcinomas, and this decrease was associated with tumor size (>5 cm) and body weight loss (>3 kg)." (PMID 37373115, 2023). "Moreover, a plasma NPY decrease in patients with colorectal or gastric carcinomas has been related to body weight loss and tumor size." (PMID 37373115, 2023). "DNA methylation sequencing analysis for gastric cancer and myelodysplastic syndrome further showed that NPY is regulated by its DNA methylation level." (PMID 36081667, 2022).
glaucoma (4 papers, 2015 to 2024). Increased pressure in the eyeball due to obstruction of the outflow of aqueous humor. "This study investigated the neuroprotective effects of NPY in a mouse model of glaucoma characterized by elevated intraocular pressure (IOP) and progressive retinal ganglion cell degeneration." (PMID 39114576, 2024). "This study investigated the role of NPY and its receptors in glaucoma and revealed neuroprotective ability in countering retinal degenerative changes caused by elevated IOP in the mouse model." (PMID 39114576, 2024). "Specifically, a distinct decrease in its immunoreactivity was observed in the GCL, suggesting a potential correlation between NPY levels and the pathogenesis of glaucoma." (PMID 39114576, 2024). "This study aimed to explore the therapeutic potential of NPY in glaucoma treatment, potentially offering a novel approach to preserving vision in individuals affected by this condition." (PMID 39114576, 2024). "In conclusion, this study highlighted the effectiveness of NPY treatment in preserving inner retinal health, reducing neuroinflammation, and preventing axonal damage in a glaucoma animal model." (PMID 39114576, 2024). "This comprehensive impact of NPY, mitigating both retinal and optic nerve inflammation, reinforces its potential as a therapeutic agent in glaucoma treatment." (PMID 39114576, 2024). "ELISA tests on retinal samples further confirmed significantly lower NPY levels in both human glaucomatous retinas and mouse models of induced glaucoma." (PMID 39114576, 2024). "However, given that human glaucoma likely includes a vascular component, understanding NPY's action on the retinal vasculature is critical." (PMID 39114576, 2024). "In addition, since RGCs are lost in retinal degenerative diseases such as glaucoma, we also evaluated the neuroprotective potential of NPY against excitotoxic or ischemia-reperfusion (I-R) injuries." (PMID 26311075, 2015). "Given NPY's potential as a therapeutic target for various degenerative conditions, this study hypothesized that NPY administration could protect RGCs from degenerative changes in a glaucoma animal model." (PMID 39114576, 2024). "NPY exerts neuroprotective actions in various brain regions, and also in the retina, suggesting that NPY receptors might be possible therapeutic targets for retinal degenerative diseases such as glaucoma." (PMID 26311075, 2015). "This study also explored the involvement of NPY in the PI3K/Akt signaling pathway, which is crucial for cell survival and metabolism, particularly in the context of glaucoma." (PMID 39114576, 2024). "However, the physiological role of NPY in trabecular meshwork cells is not clearly understood which warrants a detailed investigation to understand its role in GC-OHT and glaucoma." (PMID 35585182, 2022). "While NPY has been studied in many acute toxicity models, such as glutamate and 3,4-methylenedioxymethamphetamine toxicity, its protective effects in chronic degenerative models like glaucoma have not been explored." (PMID 39114576, 2024).